BRCA1 (BRCA1 DNA repair associated)
Diseases named in the same sentence as BRCA1 in open-access papers (continued):
Sharing a sentence is not in itself a finding about the gene and the disease.
serous ovarian cancer (continued). "While BRCA1 promoter methylation is associated with HRD and is present in a subset of high-grade serous ovarian cancer (HGSOC) cases, findings from the TCGA study, indicate that BRCA1 promoter methylation was not highlighted as an independent prognostic marker for patient outcomes." (PMID 40069561, 2025). "Similarly, in UWB1.289, a BRCA1-mutant high-grade serous ovarian cancer (HGSOC) cell line, TLK1 or TLK2 depletion decreased sensitivity to olaparib and niraparib." (PMID 39844055, 2025). "Therefore, this study aimed to investigate the prevalence of germline mutations in BRCA1 and BRCA2 genes among women with high-grade serous ovarian cancer (HGSOC) treated in the Public Health System in Recife, Pernambuco." (PMID 38641594, 2024). "We confirmed that HUWE1 silencing leads to PARPi resistance using either talazoparib or olaparib in parental SUM149 cells (without sg-GFP) and in another tumour cell line with a pathogenic exon 11 frameshift BRCA1 mutation, UWB1.289 (high grade serous ovarian cancer, referred to as UWB1)." (PMID 37491606, 2023). "Interestingly, BDP1 expression decreased as serous ovarian cancer stage similar to BRCA1 (F = 3.81; Pr(>F) = 2.3 × 10−2) and BRCA2 (F = 12.8; Pr(>F) = 3.95 × 10−6)." (PMID 36305848, 2023). "The treatment of high-grade serous ovarian cancer and high-grade endometrioid ovarian cancer has seen significant improvements in recent years, with BRCA1/2 and homologous recombination status guiding a personalized approach which has resulted in improved patient outcomes." (PMID 36643655, 2023). "To this aim, we tested in the present study the sensitivity of 8 PDX models, comprising 7 TNBC (2 BRCA1-WT, 4 BRCA1-methylated (BRCA1-Me), 1 BRCA1-Mut) and 1 BRCA1-Mut High Grade Ovarian Serous Ovarian Carcinoma (HGSOC), to the PARP inhibitor olaparib and to carboplatin (CBP)." (PMID 37007122, 2023). "Indeed, NGS revealed that beyond BRCA1/2, mutations in HR effectors, such as PALB2, RAD51, ATM, BRIP1, BARD1, and CHEK2 occurs in up to a fifth of the patients with high-grade serous ovarian cancer." (PMID 36010882, 2022). "In high-grade serous ovarian cancer (the most common subtype), 18–30% of all BRCA mutations are reported to be somatic, and when broken down into individual genes, rates of 28 and 26% have been reported for BRCA1 and BRCA2, respectively." (PMID 34979999, 2022). "Finally, a fourth study evaluating the outcomes of germline BRCA1/2m in patients with advanced high-grade serous ovarian cancer revealed longer progression-free survival compared to patients without germline mutations." (PMID 35909902, 2022). "BRCA1 promoter hypermethylation occurs in 10–20% of high-grade serous ovarian cancers." (PMID 35008360, 2021). "However, about 50% of high grade serous ovarian cancers (HGSOC) present with HRD due to epigenetic BRCA1 inactivation, as well as genetic/epigenetic inactivation(s) of other HR genes, a feature known as “BRCAness”." (PMID 33213473, 2020). "Indeed, BRCA1-mutant, high-grade serous ovarian cancers present a specific molecular subtype with a distinct gene expression signature, which seems related to specific amplification events at 8q24 and on the X chromosome." (PMID 31130614, 2019). "This association between BRCA1 and key molecules of EMT might explain why patients carrying mutations in BRCA1 develop mainly aggressive and dedifferentiated serous ovarian cancers." (PMID 31213009, 2019). "High-grade serous ovarian cancers (HGSOCs) have defects in homologous recombination despite a lack of BRCA1/2 mutations." (PMID 31604914, 2019). "Since mutations in the BRCA1/2 genes, involved in DDR, are common in high-grade serous ovarian cancer, and increase mutational burden, thus the correlation between miR-211 expression and mutation burden might be influenced by the BRCA mutation status." (PMID 31235732, 2019).
serous ovarian cancer (continued). "BRCA1 methylation is detected in 9-15% of spontaneous cases of serous ovarian cancer, but does not seem to occur in concert with germline mutations." (PMID 31225507, 2019). "Potential reasons for this difference could be the higher prevalence of patients with triple negative breast and high-grade serous ovarian cancers, which harbored germline BRCA1 mutant tumors." (PMID 29262651, 2017). "Women with a strong family history of “serous ovarian cancer”, but no identified BRCA1 or BRCA2 mutation in the family, also have elevated risks of PSC." (PMID 28285341, 2017). "In addition, high rates of somatic and germline genomic defects in BRCA1/2 and other homologous recombination genes overall, as well as a high percentage of gene copy number variations have been reported in high-grade serous ovarian cancer." (PMID 27983698, 2016). "Hypermethylation of BRCA1 was detected at a significantly higher frequency in serous carcinomas than in tumors of the other histological types, with earlier onset of high-grade serous ovarian cancer." (PMID 25986046, 2015). "The effects of BRCA1 on IGF1R were assessed in 121 serous ovarian cancer patients (BRCA1 mutation, n=30; non-BRCA1 mutation, n=32; hypermethylated BRCA1 promoter, n=28; and non-methylation, n=31)." (PMID 24765210, 2014). "The regulatory effects of BRCA on GR were assessed in 146 serous ovarian cancer patients (28 pairs of BRCA1-mutated or not, 23 pairs of BRCA2-mutated or not, and 22 pairs with hypermethylated BRCA1 promoter or not)." (PMID 24629067, 2014). "In phase II clinical trials conducted in high-grade serous ovarian carcinomas, olaparib has been reported to be effective in certain patients without BRCA1/2 mutations." (PMID 24625059, 2014). "The effect of BRCA1 on EGFR was assessed in 146 serous ovarian cancer patients (28 pairs of BRCA1-mutated or not, 23 pairs of BRCA2-mutated or not, and 22 pairs with hypermethylated BRCA1 promoter or not)." (PMID 24321281, 2013). "In this regard, one study found very similar miRNA expression profiles in high grade serous ovarian carcinomas with or without BRCA1/2 mutations." (PMID 22701724, 2012). "By comparing the prevalence of occult tumors at each stage to the incidence of serous ovarian cancer in a matched population of women (BRCA1 carriers, similar age), we estimated that serous tumors spend approximately 4.3 y as histopathologically detectable but clinically occult early stage tumors." (PMID 19636370, 2009). "Whether our findings in BRCA1 carriers can be generalized to serous ovarian cancers in general, including sporadic or non-BRCA1 familial cases, is still an important question." (PMID 19636370, 2009).
serous ovarian cancer (continued). "This study aimed to investigate the efficacy of HRD testing in high-grade serous ovarian carcinoma, tubal, and peritoneal cancer patients who are negative for somatic BRCA1 and BRCA2 mutations and to evaluate the impact of HRD status on Bevacizumab and PARPi therapy response." (PMID 37296748, 2023). "In addition, the molecular and genetic features of a cohort of 87 patients with high-grade serous ovarian cancer (HGSOC) harboring BRCA1/2 mutations without reversion mutations were compared with those of 14 patients with HGSOC and reversion mutations." (PMID 36557020, 2022). "Risk‐reducing bilateral salpingo‐oophorectomy (RRBSO) is highly effective for the prevention of high‐grade serous ovarian cancer (HGSOC) in BRCA1/2 pathogenic variant carriers (PVCs), but does not completely eliminate future risk of primary peritoneal cancer (PPC)." (PMID 33152107, 2021). "Women with germ-line BRCA1 or BRCA2 mutation are at increased risk of developing ovarian serous carcinoma while a subset of non-familial ovarian serous carcinomas also demonstrate loss of BRCA1 through either somatic mutations or promoter methylation with transcriptional silencing." (PMID 19798417, 2009). "Notably, as an alternative to mosaic pathogenic genetic variants, we have also recently found constitutional mosaic promoter methylation of BRCA1 to be associated with a significantly increased risk of triple‐negative breast cancer and high‐grade serous ovarian cancer." (PMID 40072281, 2025). "High-grade serous ovarian cancer (HGSOC) is a poor prognostic disease, especially in BRCA1/2 wild-type (BRCA-WT) patients with homologous recombination (HR) proficiency." (PMID 41354716, 2025). "Contrasting BRCA2, epimutations in the BRCA1 gene are frequently detected in tissue from triple-negative breast (TNBC) and high-grade serous ovarian cancers (HGSOC)." (PMID 40225940, 2024). "Relative de novo sensitivity to artesunate was evaluated in a panel of human high-grade serous ovarian cancer cell lines including CAOV3, OVCAR3, OV-90, and BRCA1-null UWB1.289 cells." (PMID 38610999, 2024). "In high‐grade serous ovarian carcinoma (HG‐SOC), high expression of miR‐182 promotes tumorigenesis by targeting Breast Cancer Gene 1 (BRCA1), High Mobility Group AT‐Hook 2 (HMGA2), and Metastasis Suppressor 1 (MTSS1) genes." (PMID 39617640, 2024). "Together, these data suggest potential cross‐talk between BRCA1 and BDP1 activity in late‐stage serous ovarian cancer as a component of the oncogenic network driving proliferation." (PMID 36305848, 2023). "Together, these data suggest that only BDP1 of the TFIIIB complex has expression correlating with stages II, III and IV in serous ovarian cancer which interestingly, is similar to BRCA1 and BRCA2, established drivers of serous ovarian cancer." (PMID 36305848, 2023). "Using the cBioPortal and the same TCGA dataset, we note that BRCA1 (4%) and BRCA2 (5%) are altered in serous ovarian cancer, and the alterations include amplifications and homodeletions." (PMID 36305848, 2023). "Reflex (automatic) BRCA1 and BRCA2 (BRCA1/2) genetic testing of tumour tissue is being completed for all newly diagnosed high-grade serous ovarian cancer (HGSOC) in the province of Ontario, Canada." (PMID 35418215, 2022).
serous ovarian cancer (continued). "In the present study, we examined the methylation status of six gene promoters (BRCA1, CST6, MGMT, RASSF10, SLFN11 and USP44) in high-grade serous ovarian cancer (HGSOC)." (PMID 35008168, 2021). "According to the results of the II generation, we compared the gene sequencing of 3326 bases of BRCA1 gene and the 1342 bases of BRCA2 gene in all females of the III generation in the family and 2 patients with sporadic serous ovarian cancer (control)." (PMID 32356124, 2020). "A total of 128 patients diagnosed with FIGO stage III-IV high-grade serous ovarian cancer (HGSOC) between 2008 and 2017 and underwent BRCA1/2 gene testing at the time of or within two years from cancer diagnosis were included in this study." (PMID 31064392, 2019). "We used a commercial kit exploring all exons and 50bp exon-intron junctions of BRCA1 and BRCA2 genes, and semiconductor next-generation sequencing (NGS) on DNA from 47 FFPE samples of high-grade serous ovarian cancers." (PMID 26745875, 2016). "According to several studies, the high level of genomic structural alterations is characteristic of BRCA1 or BRCA2 inactivation (so called BRCAness) in triple-negative breast and serous ovarian carcinomas." (PMID 26426992, 2015). "Here, we discuss a therapeutic concept that seeks to disrupt HR capacity via targeting of BRCA1 and BRCA2 functionality in order to reverse platinum resistance in BRCA-proficient high-grade serous ovarian cancers (HGSOC)." (PMID 24624361, 2014). "Approximately 50% of high-grade serous ovarian cancers exhibit HRD, even in the absence of germline or somatic BRCA1/2 loss-of-function mutations." (PMID 40007558, 2025). "Additionally, gene variations containing the BRCA1 gene and BRCA2 gene augment the possibility of a high-degree serous ovarian carcinoma circumstance." (PMID 39199599, 2024). "High-grade serous ovarian cancers with germline or somatic mutations in BRCA1 or BRCA2 genes and hypermethylation of the BRCA1 gene and NSCLC without ERCC1 are sensitive to platinum compounds." (PMID 36499000, 2022). "In the gene list, BRCA1/BRCA2 were reported and may promote neoepitope formation in high-grade serous ovarian cancer." (PMID 35205408, 2022). "Mutations of BRCA1/2 are well-known as the most frequent mutations to occur in OC, mainly in high-grade serous ovarian carcinoma (HGSOC); however, reports of BRCA1/2 mutations in individual EOVC cases are not common." (PMID 34150634, 2021). "Whereas some authors reported reliable IHC modalities in high-grade serous ovarian carcinomas, others argue that IHC staining is not robust enough to be used as a screening test for detection of BRCA1 dysfunction." (PMID 32235500, 2020). "This indicates that BRCA1 inactivation is not the only mechanism for the development of aneuploidy in high-grade serous carcinoma of the ovary." (PMID 20843305, 2010). "No apparent separation between high grade ovarian serous carcinomas of different BRCA1/2 status was noted." (PMID 19798417, 2009). "High grade serous ovarian carcinomas with and without BRCA1/2 abnormalities demonstrate very similar miRNA expression profiles." (PMID 19798417, 2009). "High grade serous ovarian cancers that have functional BRCA1 or BRCA2 are currently not separable from high grade serous cancers that have loss of function of these proteins, based on routine histopathological examination." (PMID 18208621, 2008). "The term “pelvic serous cancer” is used because the majority of BRCA1- and BRCA2-related gynaecologic cancers appear to originate in the fimbrial end of the fallopian tube rather than the ovary, although they have typically been labelled as “serous ovarian cancer” at diagnosis." (PMID 28285341, 2017).
serous ovarian cancer (continued). "High-grade serous ovarian cancer in carriers of BRCA1 or BRCA2 has a better prognosis than the same disease in non-carriers, and may be more sensitive to cisplatin-based chemotherapy or to PARP inhibitors that target DNA repair." (PMID 24265793, 2013). "While the 3 fallopian tube samples and 3 of the 4 serous borderline tumors/low grade serous carcinoma samples clustered together, there was again no apparent separation seen among the high grade ovarian serous carcinomas with respect to BRCA1/2 status or tumor stage." (PMID 19798417, 2009). "In addition, this panel is targeting “hotspot” region of genes that are frequently mutated in human cancer thus other infrequently altered genes but of significance to serous ovarian cancers might have been excluded such as ARID1A, BRCA1, BRCA2, CSMD3, NF1, CDK12, FAT3 and GABRA6." (PMID 25404506, 2014). "Given the clinical benefits demonstrated in this study, both the FDA and EMA approved rucaparib for the maintenance treatment of high-grade serous ovarian cancer (HGOC), regardless of BRCA1/2 status." (PMID 40395324, 2025). "Analysis of the GEPIA platform demonstrates that both BRCA1 and BRCA2 mRNA are overexpressed in serous ovarian cancer, but this overexpression is not statistically significant." (PMID 36305848, 2023).